SIRPA (signal regulatory protein alpha)
Diseases named in the same sentence as SIRPA in open-access papers (continued):
Sharing a sentence is not in itself a finding about the gene and the disease.
tumor (continued). "The engineered exosomes expressing SIRPα was able to antagonize CD47 on tumor cells in vitro, and they successively accumulated at tumor sites, inhibiting tumor growth in vivo." (PMID 33374978, 2020). "The inhibitory receptor signal regulatory protein-α (Sirpα) is a myeloid-specific immune checkpoint that engages the “don’t eat me” signal CD47, which is expressed on tumor and normal tissue cells." (PMID 32296015, 2020). "Sirpα/CD47 axis blocks phagocytosis, preventing the destruction of self-tissues; however, in the tumor context, the upregulation of CD47 by neoplastic cells represents a mechanism to escape immune clearance." (PMID 32962159, 2020). "In LLC tumor models, tumor weight in VEGFR1-Fc and SIRPα-Fc co-treatment group was 15.11 ± 9.03 mg versus 320.02 ± 43.3 mg of VEGFR1-Fc group (P < 0.0001)." (PMID 31829270, 2019). "When using SIRPα-Fc to block the interaction between SIRPα and CD47, alone or in combination with rituximab, phagocytosis of tumor cells was differentially increased in the three Mo/MΦ subsets." (PMID 31611550, 2019). "Tumor weight in PBS/liposome + IgG1-Fc group, PBS/liposome + VEGFR1-Fc group, PBS/liposome + SIRPα-Fc group, PBS/liposome + VEGFR1-Fc + SIRPα-Fc group were 916.62 ± 113.49 mg, 516.00 ± 78.29 mg, 360.20 ± 68.34 mg, 112.12 ± 28.84 mg." (PMID 31829270, 2019). "For instance, the blocking of CD47-SIRPα interaction using anti-CD47 monoclonal antibodies, anti-SIRPα antibodies, or nanobodies, has shown delayed tumor progression." (PMID 31882679, 2019). "While tumor weight in Clo/liposome + IgG1-Fc group, Clo/liposome + VEGFR1-Fc group, Clo/liposome + SIRPα-Fc group and Clo/liposome + VEGFR1-Fc + SIRPα-Fc group were 950.01+ 147.82 mg, 528.16 + 134.24 mg, 814.66 ± 145.58 mg and 513.98 + 84.44 mg." (PMID 31829270, 2019). "Humanized MAbs and a SIRPα-Fc decoy receptor targeting CD47 are now in early stages of clinical development based on the compelling body of preclinical results and human tumor expression data." (PMID 31276567, 2019). "Subcutaneous mouse tumor models and a mouse bone marrow-derived dendritic cell (BMDC) cross-presentation assay were used to assess the efficacy of SIRPα blockade in solid tumors." (PMID 30400822, 2018). "RRx-001 was shown to downregulate CD47 and SIRPα expression on tumor cells and macrophages, respectively, and to promote the phagocytosis of high-expressing CD47 A549 tumor cells." (PMID 30400835, 2018). "By engaging SIRPα, CD47 limits the ability of macrophages to engulf tumor cells, acting as a major phagocytic barrier." (PMID 29850495, 2018). "The ImmunoINTEL panels were complemented with drop-in IMR and IMR-L markers (PD1/PDL1, TIGIT/CD112-CD155, TIM-3/Galectin-9, SIRPa/CD47, LAG-3/HLADR) to profile the functional status of TILs, and to study the cytotoxic potential of tumor TILs." (PMID 30400835, 2018). "Tumor cells express CD47, which can interact with the macrophages' SIRPα transmitting a “don't eat me” signal to macrophages." (PMID 30525058, 2018). "Dual downregulation of CD47 and SIRPα by RRx- 001 results in TAM repolarization and phagocytosis of tumor cells." (PMID 30400835, 2018). "SIRPα binds with CD47 and delivers a “don’t eat me” signal for phagocytic cells to help tumor cells escape from immune clearance." (PMID 30105024, 2018). "Binding of CD47 with SIRPα on macrophages and DCs conveys a “don't eat me” signal and accordingly, the blockage of CD47-SIRPα binding induces tumor regression by activating macrophages and DCs." (PMID 27283989, 2017). "The expression of SIRPα and CD47 are varies during infection and malignancies, and they are involved in the pathogenesis of various tumor, such as melanoma, leukaemia, lung cancer." (PMID 27793032, 2016). "Macrophages were co-cultured with tumor cells in the presence of PPRHs to silence CD47 and/or SIRPα." (PMID 27671753, 2016).
tumor (continued). "The aims of this study were: to decrease the levels of CD47 in tumor cells and SIRPα level in PMA-differentiated THP-1 cells with PPRHs and ultimately to eliminate tumor cells by macrophages by diminishing the CD47/SIRPα interaction in co-culture experiments." (PMID 27671753, 2016). "In this study, we used Polypurine reverse Hoogsteen hairpins (PPRHs) as a gene silencing tool to decrease CD47 in tumor cells and SIRPα in PMA-differentiated THP-1 cells with the aim to decrease their interaction and to eliminate tumor cells." (PMID 27671753, 2016). "Indeed, blockade of PD-1 increased the expression levels of co-stimulatory molecular in mouse tumor and immune organ suggesting the condition of immune suppression was improved in the tumor microenvironment, which may be caused by decreased CD47/SIRPα signaling." (PMID 26573233, 2015). "On the one hand, antibodies targeting CD47 or SIRPα, recombinant SIRPα, or TSP1-derived proteins promote phagocytosis and tumor cell elimination by disrupting the CD47–SIRPα interaction and/or inducing Fc-dependent mechanisms or PCD." (PMID 25734483, 2015). "Subcutaneous tumor formation of Col26 increased the serum concentration of CCL2, which was deposited in IVRs and attracted Sirpα+ cDCs therein." (PMID 22815949, 2012). "CCR2 expression by Sirpα+ cDCs prompted us to examine the function of Sirpα+ cDCs in tumor-bearing mice, because CCR2 ligands, particularly CCL2, are abundantly expressed in tumor-bearing mice." (PMID 22815949, 2012). "Given the broad distribution and functional relevance of SIRPα, this study further evaluated its expression in immune cells within the tumor microenvironment rather than in tumor cells." (PMID 40926176, 2026). "Moreover, SIRPA-KO protected macrophages from mAb- and CAR-driven hypophagia, enabling efficient tumoricidal effects even after serial tumor exposures." (PMID 42291136, 2026). "The expression of SIRPA, LILRB1, LILRB2, Siglec1, Siglec7, Siglec9, PDCD1, CD163 and MARCO are preferentially expressed on Mono01, Mono02 and Macro03, suggesting their tumor-promoting roles." (PMID 40755770, 2025). "CD47 is often overexpressed on tumor cells, where it binds to SIRPα on macrophages to transmit an inhibitory “do not eat me” signal that suppresses phagocytosis and promotes immune evasion." (PMID 41402667, 2025). "The anti-tumor function of macrophages can be activated by low dose-radiotherapy or through the removal of the “don’t eat me” signal CD47 on tumor cells, which can be recognized by the receptor signal regulatory protein α (SIRPα) on macrophages." (PMID 41375050, 2025). "Our model can fit their MC38-OVA tumor growth data in WT mice with RT and anti-CD47 or anti-SIRPα." (PMID 41296731, 2025). "Recent studies have developed magnetically guided nanosystems by covalently conjugating anti-CD47 antibodies onto the surface of silica-coated IONPs, enabling their enrichment at metastatic tumor sites and effectively blocking the interaction between tumor cell-expressed CD47 and macrophage SIRPα." (PMID 41280655, 2025). "Orthotopic and subcutaneous tumor models were established with or without anti-SIRPα antibody treatment." (PMID 40523887, 2025). "We fix these parameters when we calibrate RT-related parameters of tumor growth in WT with RT, and SIRPα− macrophage related parameters using tumor growth data in SIRPα−/− mice without RT." (PMID 41296731, 2025). "Therefore, our findings highlight miR-96-5p as a crucial tumor suppressor in the progression of PDAC, with biological, mechanistic and clinical effects on human PDAC and the CD47/SIRPα signaling pathway." (PMID 41350707, 2025). "In summary, our SIRPα-αMSLN LicMAb constructs show promising activity without on-target off-tumor toxicity in preclinical models." (PMID 40402266, 2025). "Additionally, SIRPα and Siglec-5 recruit SHP-1 and SHP-2 to inhibit SYK phosphorylation, potentially facilitating tumor immune evasion." (PMID 40858654, 2025).
tumor (continued). "The immune checkpoint axis formed by SIRPα, expressed on phagocytes including TAMs, and CD47 on tumor cells inhibits intracellular signaling cascades, thereby negatively regulating phagocytic activity and enabling tumor cells to evade immune elimination." (PMID 40563367, 2025). "Notably, when comparing SIRPα and PDL-1 expression on these TAMs subsets between tumor biopsy and CUSA tumor fragments from the same patients, either in fresh or cryopreserved samples, similar trends were observed." (PMID 40980437, 2025). "Because neither F05 and 1H9 bind the murine SIRPα, we generated models in which subcutaneous tumors are formed with a combination of Raji tumor cells and human M2 macrophages as effectors." (PMID 40408355, 2025). "Unlike antagonistic molecules targeting CD47 or SIRPα directly, small-molecule inhibitors for this pathway do not compete with natural binding partners in the tumor microenvironment." (PMID 40589735, 2025). "SIRPα activation recruits SHP-1 and SHP-2, leading to their phosphorylation, which in turn dephosphorylates SYK and suppresses its activation, affecting immune cell anti-tumor functions." (PMID 40858654, 2025). "A small dose of SIRPα antibody is sufficient to block the CD47-SIRPα pathway in tumor cells without leading to erythrocyte destruction or other hematological adverse effects." (PMID 40356928, 2025). "Furthermore, TAMs overexpress signal regulatory protein-α (SIRPα), which interacts with the “don’t eat me” signal CD47 on tumor cells." (PMID 40177538, 2025). "CD47, overexpressed on tumor cells, interacts with SIRPα on macrophages, delivering a “do not eat me” signal that inhibits phagocytosis." (PMID 40806636, 2025). "Coculture with CAR-modified macrophages increased apoptosis in nonphagocytosed tumor cells, and SIRPα inhibition further augmented this effect." (PMID 39379603, 2024). "The evaluation of the anti-tumor effects of SIRPα-VEGFR1, a bispecific fusion protein that concurrently inhibits CD47 and VEGF, demonstrated significant tumor regression in the Hu-PDX1 model, comparable to the observed effects in the SIRPα-Fc + VEGFR1-Fc combination group." (PMID 38532108, 2024). "Thus, by disrupting with the SIRP-α-CD47 axis (e.g., by using antibodies against SIRPα and CD47), it is possible to restore recognition and phagocytosis of tumor cells by TAMs, and to activate anti-tumor immune responses." (PMID 39065562, 2024). "The results of the flow cytometry analysis showed that compared to IMM01 (SIRPα Fc fusion protein), all CD38/CD47 BsAbs had a greater ability to bind to CD38+ tumor cell lines in a concentration-dependent manner, and the binding ability of 35G5 and 12C10 was greater than that of the other BsAbs." (PMID 38983860, 2024). "Single-agent therapy with either SIRPα-Fc or VEGFR1-Fc could inhibit tumor growth to some extent but eventually, the tumor growth progressed and resisted the treatment." (PMID 39335665, 2024). "Engagement of SIRPα with CD47 on myeloid cells contributes to the generation of an immune-suppressive environment by reducing sampling, processing, and presentation of tumor-derived antigen to infiltrating T cells." (PMID 38577107, 2024). "We established a MC38 tumor model, which is characterized by an abundance of intra-tumoral macrophages, to assess the antitumor potential of SMC18, a small molecule inhibitor targeting both CD47/SIRPα and PD-1/PD-L1 interactions." (PMID 38462636, 2024). "We have focused on the two immune checkpoints, PD-1/PD-L1, the “Do not kill me signal”, and CD47/SIRPα, the “Do not eat me signal”, to examine the kinetics of tumor immunity in the tumor microenvironment of OSCC." (PMID 38612630, 2024). "In addition, tumor cell surfaces widely express CD47, which can bind to signal-regulatory protein α (SIRPα) on macrophages to inhibit phagocytosis." (PMID 38167055, 2024).
tumor (continued). "The ligand of CD47, signal regulatory protein alpha (SIRPα), is mainly expressed on macrophages and when the interaction with CD47 occurs, the downstream signaling within tumor cells results in the dephosphorylation of multiple substrates, keeping tumor cells from phagocytosis by macrophages." (PMID 39003350, 2024). "In most tumors, signal regulatory protein α (SIRPα) on the surface of macrophages often interacts with CD47 (a "don't eat me" signal) on the surface of tumor cells, limiting the ability of macrophages to phagocytose tumor cells." (PMID 38281957, 2024). "Finally, we tested the anti-tumor effect of co-targeting CD47 and angiogenesis using a bispecific fusion protein, SIRPα-VEGFR1, which successfully inhibited tumor growth to a similar extent as a combination therapy." (PMID 39335665, 2024). "Tumor cells express the “do not eat me” signal CD47 to interact with SIRPα on macrophages, which contributes to escape immune elimination." (PMID 39516356, 2024). "The extracellular N-terminal IgV domain of CD47 is essential for interacting with the signal regulatory protein α (SIRPα) on the surface of macrophages and dendritic cells, which aids high-CD47-expressing tumor cells and circulating hematopoietic stem cells in avoiding phagocytosis." (PMID 38426113, 2024). "CD47 expressed on the surface of tumor cells binds to SIRPα on the surface of macrophages, leading to phosphorylation of the immune receptor tyrosine inhibitory motif (ITIM) in the intracellular domain of SIRPα." (PMID 38429732, 2024). "We then evaluated the in vivo therapeutic efficacy of SIRPα-Fc in the HSPCs-CDX model, which could better simulate the anti-tumor effect of CD47 blockade in a human immune system." (PMID 39335665, 2024). "Unlike stimulating T-cell activity, the CD47–Signal regulatory protein alpha (SIRPα) axis functions as a regulatory point for tumor phagocytosis." (PMID 38543240, 2024). "More importantly, within SPP1 + macrophages, SIRPα positive cells exhibited enhanced phagocytic potential and were in closer proximity to both tumor cells and CD8 + T cells compared to SIRPα negative cells." (PMID 39696410, 2024). "First, macrophages and related myeloid cells with both SIRPα blockade and FcR-engaging, tumor-targeting IgG maximize survival of mice with WT B16+Rev tumors – noting that macrophages express SIRPα and FcRs, but most or all T cells do not." (PMID 38805560, 2024). "During the development of tumors, tumor cells transmit a “don’t eat me” signal through the up-regulation of CD47 and its binding to signal regulatory protein α (SIRPα) on the surface of antigen-presenting cells (APCs) via the CD47-SIRPα pathway." (PMID 38324678, 2024). "Another novel strategy uses anti-CD47 antibodies that block the “do not eat me” CD47 and signal regulatory protein alpha (SIRPα) interactions that allow for tumor cell evasion of phagocytosis." (PMID 38612926, 2024). "Targeting of SIRPα, the binding partner of CD47, may therefore offer a safer alternative approach with which to modulate myeloid-driven anti-tumor immunity, as it is almost exclusively expressed by the myeloid compartment." (PMID 38577107, 2024). "Blocking SIRPα on the surface of TAMs and DCs, which blocks its interaction with CD47 on the surface of tumor cells and their subsequent “don’t eat me” signal, restores the phagocytosis of tumor cells." (PMID 38433837, 2024). "These CD38/CD47 BsAbs could selectively block the interaction between CD47 and SIRPα on CD38+/CD47+ tumor cells and induce tumor cell death in vitro and in vivo." (PMID 38983860, 2024). "The CD47/SIRPα axis, which is engaged in macrophage-tumor immune escape, was not significantly affected by morphine." (PMID 37259426, 2023). "As demonstrated in the tumor model, the binding between the transmembrane protein CD47 and the signal regulatory protein alpha (SIRPα) prevents phagocytosis of EVs by macrophages, thus increasing their blood concentration and improving their delivery to target sites." (PMID 36769247, 2023).
tumor (continued). "CD47 interacts with several receptors and molecules, including TSP-1 and SIRPα, to activate downstream pathways such as Akt/mTOR, NF-κB, PI3K/Akt, RhoA/ROCK, and others, to regulate cellular processes such as tumor cell survival, invasion, angiogenesis, cell migration, and apoptosis." (PMID 38188674, 2023). "In addition to inhibiting binding between CD47 and SIRPα, antibodies targeting CD47 have the potential added benefit of blocking tumor-promoting cell-intrinsic CD47 signaling, but at the cost of challenges associated with the CD47 antigen sink." (PMID 37958404, 2023). "CD47-SIRPα pathway: CD47 is an inhibitory ligand on tumor cells that binds to the signal-regulatory protein alpha (SIRPα) on macrophages, acting as a “do not eat me” signal to prevent phagocytosis." (PMID 38258072, 2023). "Investigators have identified several tumor-phagocytosis-related checkpoints, including the CD47/signal regulatory protein α (SIRPα) axis, the PD-1/PD-L1 axis, the MHC-I/leukocyte immunoglobulin-like receptor subfamily B (LILRB1) axis, and the CD24/SIGLEC10 axis." (PMID 38033495, 2023). "OAd-SIRPα-Fc treatment conferred better antitumor activity than OAd-Siglec10-Fc and OAd-TIGIT-Fc in the MC38 model, but OAd-Siglec10-Fc showed satisfactory tumor suppression in the 4T1 model." (PMID 38016957, 2023). "The CD47-SIRPα pathway on tumor cells prevents phagocytosis by binding to macrophage SIRPα, serving as a “do not eat me” signal." (PMID 38258072, 2023). "Because mCD47 does not cross-react with human-SIRPα (hSIRPα), the mouse-derived tumor cell lines were humanized via stable transfection with full-length hCD47 (Cell-hCD47)." (PMID 36650558, 2023). "Signal regulatory protein α (SIRPα) on the surface of macrophages can help macrophages recognize “myself” and “non-me” cells, and the surface of tumor cells usually highly express the CD47 molecule." (PMID 36911723, 2023). "It has been demonstrated that blockade of the CD47/SIRPα signaling alone is insufficient to inhibit tumor growth in the absence of additional pro-phagocytic signals (e.g., Fc-FcγR-mediated effector function)." (PMID 36650558, 2023). "Besides, SIRPα NOD mice lack critical mechanisms such as ADCC, which limits their use as a model for evaluating tumor immunotherapy." (PMID 37484024, 2023). "CD47 is known as a “do not eat me” signal that, following its binding with SIRPα on macrophages, prevents the macrophage-mediated phagocytosis that represents the engulfment of tumor cells by phagocytosis-specialized macrophages." (PMID 36829496, 2023). "Hence, we evaluated the effects of diHEP-DPA and 5-FU on SIRPα and CD47 expression in tumor tissues." (PMID 36827121, 2023). "SIRPα binds with CD47 to initiate a signaling cascade which results in the inhibition of phagocytosis, a critical “do not eat me” signal for the innate immune system which is overexpressed on many kinds of tumor cells." (PMID 36827121, 2023). "Signal-regulatory protein α (SIRPα) expressed by myeloid cells is of particular interest for therapeutic strategies targeting the interaction between SIRPα and the “don’t eat me” ligand CD47 and as a marker to monitor macrophage infiltration into tumor lesions." (PMID 38164132, 2023). "Furthermore, the specific binding of purified SIRPα-Fc and Siglec10-Fc to CD47 or CD24, respectively, enhanced macrophage‐mediated tumor cell phagocytosis in vitro." (PMID 38016957, 2023). "The results indicated that lack of SIRPα in KO mice reduced the population of exhausted PD‐1+CD8+ T cells in tumour tissues." (PMID 36419386, 2023). "Furthermore, Ring and colleagues have revealed a new anti-human SIRPα antibody, KWAR23, which can elevate both neutrophils and macrophages’ anti-tumor activity in vitro and in vivo." (PMID 36845095, 2023).